MMP2 (matrix metallopeptidase 2)
Diseases named in the same sentence as MMP2 in open-access papers (continued):
Sharing a sentence is not in itself a finding about the gene and the disease.
Stroke (continued). "Additionally, inhibiting MMP-2 function may provide some clues to the role of this inflammatory marker on offspring stroke outcome." (PMID 39273042, 2024). "SHS may further participate in developing both stroke subtypes by modulating various channel activities and gene expression, such as activating calcium-dependent potassium channels and upregulating matrix metalloproteinase expression (e.g., MMP-2 and MMP-9)." (PMID 38343713, 2024). "Notably, the secretion and regulation of MMP2 lead to BBB damage in the early stage of stroke." (PMID 35959401, 2022). "Moreover, brain-derived MMP-2 and MMP-9 activated by ischemia are associate with hemorrhagic transformation, partly explaining the high incidence of hemorrhage of stroke KO mice." (PMID 30622459, 2018). "MMP-2 is up-regulated in EC exposed to inflammatory cytokines such as interleukin-1-beta and growth factors including nerve growth factor, where in vivo, it promotes capillary invasion and so is probably increased in active stroke regions undergoing remodelling." (PMID 19292924, 2009). "Studies on stroke and TBI show increased levels of MMP-2 and MMP-9 after injury, with MMP-2 reducing tight-junction integrity and MMP-9 causing complete degradation of the basal lamina and tight junctions." (PMID 40806328, 2025). "Among the 23 MMPs that have been identified to date, MMP-2 and MMP-9 are the most widely studied in stroke due to their critical role involved in pathogenesis of BBB breakdown and subsequent vasogenic edema." (PMID 39273389, 2024). "Two days after stroke, MMP-9 and MMP-2 concentrations were significantly higher in ischemic lesions in comparison with non-ischemic lesions and, additionally, an elevated level of MMP-9 was found also in the ischemic penumbra." (PMID 36835040, 2023). "In studies conducted in both animal and human brains, after stroke or after experimental middle cerebral artery occlusion (MCAO) in comparison with controls, increased levels of MMP-2, -3 and -9 were demonstrated." (PMID 36835040, 2023). "MMP-13 has been shown to have a similar pattern to MMP-2 and MMP-9, i.e., it promotes HT in the acute phase of stroke and is involved in the regeneration of damaged tissue in the late phase." (PMID 37511788, 2023). "Plasma MMP‐2 levels on admission negatively correlate with NIHSS scores, and patients with better outcomes have higher MMP‐2 levels, suggesting that MMP‐2 has a positive effect on stroke outcomes." (PMID 37452512, 2023). "In the patients whose autopsy material was analyzed several months or years after stroke, the activity of MMP-9 was increased to a much lesser extent in the foci, though, at the same time, increased activity of MMP-2 was observed." (PMID 37511788, 2023). "Matrix metalloproteinase-2 (MMP-2) is one of the most studied enzymes concerning their changes in peripheral blood concentration both in acute and chronic phases of post-stroke symptoms." (PMID 36312038, 2022). "There is still great research value for the four more meaningful stroke-related proteins (STAT3, MMP2, ESR1, TERT) in this study, and pointed out the direction for our further research." (PMID 36133785, 2022). "Treatments with resveratrol and EGCG have been shown to attenuate Aβ1–40 and slow cognitive decline in AD patients, and in stroke patients, reduce the levels of matrix metalloproteinase-9 (MMP-9) and matrix metalloproteinase-2 (MMP-2)." (PMID 35204290, 2022). "For example, matrix metalloproteinase-2 (MMP-2) activity, cyclooxygenase-2 (COX-2), IL-1β, and IL-6 were increased in the diabetic mouse brain after stroke." (PMID 33728336, 2021). "We further studied such complexes using markers for tight-junction proteins (occludin and claudin-5) and proteases (MMP2 and MMP9) that increase the permeability of the BBB during stroke." (PMID 32221863, 2021).
Stroke (continued). "The present study assessed the effects of two types of selected aerobic exercises prior to stroke induction and characterized the expression of TrkB, TNF-α, and MMP2 genes in vivo." (PMID 33954182, 2021). "Patients with Alzheimer’s disease, multiple sclerosis, amyotrophic lateral sclerosis, stroke, spinal cord injury, or epilepsy are known to have increased MMP-9 and MMP-2 levels in the central nervous system." (PMID 34769297, 2021). "We also found several MMP-related genes, such as MMP2 and TIMP1, to be significantly downregulated in post-stroke muscle." (PMID 32629989, 2020). "The expression of MMP2 and MMP9 (green) was detected by immunofluorescence assay in the IBZ of the brain on day 28 after stroke." (PMID 30947736, 2019). "The results verified that TSP4-BMSC treatment significantly increased the secretion of MMP2 and MMP9 post-stroke." (PMID 30947736, 2019). "CaMKK inhibition enhanced MMP2 and MMP9 activity while reducing levels of key BBB proteins in adult stroke models." (PMID 31027360, 2019). "Members of the MMPs family, specifically MMP-2 and MMP-9 are involved in the breakdown of the BBB and increased levels of these MMPs have been observed during CIRI in stroke." (PMID 31057477, 2019). "Current data suggest that MMPs (such as MMP-2 and MMP-9) mediate beneficial dendritic plasticity and ECM remodeling at delayed stages after stroke." (PMID 28290150, 2018). "There was chronic and abundant expression of MMP-2, MMP-3, and MMP-8 in the area of liquefactive necrosis following stroke compared to the equivalent area of infarction in the heart." (PMID 30417081, 2018). "The aim of this study was to further investigate the influence of multisensory brain stimulation provided by EE after stroke on PNN integrity and on changes in expression/activity of MMP-2 and MMP-9, tPA, ADAMTS-4, and their inhibitors." (PMID 28290150, 2018). "Multiple studies showed increased expression and activity of MMP-2 and MMP-9 after brain injury (such as stroke) during the recovery phase." (PMID 28290150, 2018). "tPA expression and activity in the healthy human cortex have been reported earlier and MMP-2 and MMP-9 activities have been studied in the ischemic core of stroke patients." (PMID 28290150, 2018). "These mice also developed birefringent crystals in the infarct in the weeks after stroke and had abundant expression of MMP-2, MMP-3, and MMP-8 in the area of liquefaction seven weeks following stroke." (PMID 30417081, 2018). "Without reperfusion, candesartan administration had the opposite effect and significantly reduced both MMP2 and MMP9 activity after stroke." (PMID 27127602, 2016). "This increase of nuclear gelatinolytic activity of MMP-2 and/or MMP-9 was also observed in human brain after stroke." (PMID 26925194, 2016). "MMP-2/9 has been shown to mediate BBB disruption by degrading TJ proteins such as occludin and claudin-5 in an animal stroke model and an in vitro ischemic model." (PMID 25815722, 2015). "Expression of matrix metalloproteinase (MMP) in healthy brain is relatively low, but activated MMPs, especially MMP-2 and MMP-9, increase during stroke, which leads to disruption of blood brain barrier (BBB) integrity and contributes to brain edema." (PMID 25914628, 2015). "Two specific MMPs, MMP-2 (gelatinase A) and MMP-9 (gelatinase B), have been the subjects of extensive studies in the stroke field." (PMID 25925889, 2015). "MMP-2 is responsible for early BBB disruption, while MMP-9 is involved in brain injury at relatively late stroke stages in vivo and in vitro." (PMID 25815722, 2015). "It is well known that matrix metalloproteinase (MMP) activation, in particular MMP2 and MMP9, is a critical mediator of hemorrhagic transformation after aneurysm formation and stroke." (PMID 24991237, 2014).
Stroke (continued). "Higher expression levels of COX-2, PGES, MMP-2, and MMP-9 were detected in specimens obtained from the carotid lesions of patients with recent TIA or stroke compared with specimens obtained from asymptomatic patients." (PMID 21457581, 2011). "Since the AA and AG genotypes are more frequent in the poor recovery group, we can hypothesize that the presence of the A allele may lead to an increased transcription of the MMP-2 gene, and thus explain the negative impact on stroke recovery observed in this population sample." (PMID 20222942, 2010). "Olmesartan, a AT1 receptor blocker can reduce the reactive upregulation in brain angiotensin II, MMP-2, MMP-9 and membrane type 1-MMP in the ischemic area to improve stroke index score, infarct volume, and cerebral edema in cerebral ischemia model." (PMID 20514206, 2009). "Studies suggested that level of MMP-2 and MMP-9 significantly increases in the brain after stroke." (PMID 39654616, 2024). "In contrast, MMP-2 expression in the non-stroke hemisphere was not significantly changed when comparing control and r-tPA-treated mice at all three ischemic timepoints (p > 0.05 at 1, 2, and 4 h)." (PMID 39273389, 2024). "The results of zymography showed that MMP-9 activity was markedly increased in lesions in patients 2–4 days after stroke compared to intact brain areas, whereas there was virtually no change in MMP-2 activity." (PMID 37511788, 2023). "The dynamics of MMP-2 and MMP-9 activity reflect their multifunctional roles in stroke." (PMID 37511788, 2023). "MMP-2 and MMP-9 are considered molecular biomarkers of neuroinflammation in stroke studies." (PMID 35743229, 2022). "Already, the involvement of MMP-2 and MMP-9 has been extensively studied in stroke." (PMID 34299322, 2021). "MMP-2 and MMP-9 are the most studied and main MMPs that are increased following stroke." (PMID 34483842, 2021). "They identified higher macrophage infiltration in carotid plaques, obtained from patients operated early after stroke, compared with asymptomatic patients, as well as significantly elevated levels of a set of proinflammatory cytokines and MMP8, MMP9, and MMP2 activity." (PMID 32206187, 2020). "The same neuroprotective effect, however, was not noted in mice lacking MMP-2, leading to the theory that the enzyme is instead involved in post-stroke repair." (PMID 31281252, 2019). "MMPs can degrade myelin and so the initial high production of MMP-2, MMP-3, and MMP-8 at 24 h following stroke may occur as a microglia/macrophage response to damaged myelin." (PMID 30417081, 2018). "One of the possible reason for the decrease in TRAIL levels in the acute phase of stroke might be due to the proteolytic cleavage of TRAIL (e.g., MMP2)." (PMID 29556210, 2018). "With regard to therapeutic intervention, G-CSF, IL-1β, IP-10, MCP-1, MIP-1α, MIP-1β, RANTES, TNF-α, MMP-2, and MMP-8 were substantially reduced in OPN-/- mice seven weeks following stroke, and these mice exhibited less secondary neurodegeneration in the peri-infarct location." (PMID 30417081, 2018). "In contrast, treatment with minocycline did not impair expression of MMP-2 and −3 during recovery, which are required for stroke- induced angiogenesis." (PMID 25889169, 2015). "The neuroprotective effect of minocycline is associated with its ability to interfere with MMP activity including gelatin proteolytic activation (MMP-2 and −9); minocycline reduces brain MMP-9 levels in response to microvessel damage and inflammation during the early stage after stroke." (PMID 25889169, 2015). "A synthetic MMP inhibitor (BB-1101) blocked the increase in brain MMP-2 levels, but it did not have any effect on stroke lesion size at 48 h after MCAO and had significant adverse effects on neurologic function in rats at 3 and 4 weeks after MCAO." (PMID 23565108, 2013).
Stroke (continued). "Haplotype tagging single nucleotide polymorphisms (SNPs) in the MMP-2 (N = 21) and MMP-9 (N = 4) genes were genotyped and tested for association with stroke outcome, adjusting for significant non-genetic clinical variables." (PMID 20222942, 2010). "Indeed, we found that stroke resulted in increased activity of MMPs—the main enzymes involved in ECM remodelling—which was detected by in situ zymography of CCA plaque sections and validated by gel zymography for MMP2 and MMP9." (PMID 39112714, 2024). "However, inhibition of MMP-2 and MMP-9 confers neuroprotection in stroke." (PMID 39654616, 2024). "Consistent with other findings that infiltrated neutrophils expressed MMP-9 post stroke, our double-immunostaining also showed that MMP-9 was found in infiltrated neutrophil and monocytes outside the vascular compartment, whereas MMP-2 was only detected in the vascular compartment." (PMID 39273389, 2024). "In rat stroke models, derivatives of caffeic acid such as dihydrocaffeic acid and chlorogenic acid, detected in A. borbonica, were able to reduce brain infarct and BBB damage via inhibition of the expression and activities of MMP-2 and MMP-9 in a dose-dependent manner." (PMID 35624723, 2022). "Our study demonstrated that the expression and activity of both MMP2 and MMP9 in BM animal model are upregulated by exogenous Poldip2 and downregulated by Poldip2 knockdown, corroborating the results of previous studies in hindlimb ischemia‐induced mice and stroke animal model." (PMID 32790044, 2020). "However, the levels of MMP-2 in the serum of stroke patients are not correlated to infarct size or stroke disability." (PMID 30131754, 2018). "Similarly, tPA induced MMP-2 and MMP-9 upregulation has been reported in human cerebral microvascular endothelial cell culture while increased activity and expression of MMP-9 by recombinant tPA have also been described in stroke." (PMID 23977299, 2013). "Indeed, expression of MMP-2 was 100-fold higher (4273 pg/mg), expression of MMP-3 was almost 3000-fold higher (15,059 pg/mg), and expression of MMP-8 was 500-fold higher (12,923 pg/mg) at eight weeks post stroke in the area of liquefactive necrosis compared to naïve brain tissue." (PMID 30417081, 2018). "Indeed, MMP-1 and MMP-2 appear to initiate the damage cascade early during the acute rt-PA thrombolysis phase within 2–6 h (median 3.8 h) after ischemic brain injury, and periods of enhanced BBB permeability are present at 4–8 h and again at 12–16 h after stroke onset." (PMID 30186167, 2018). "Morroniside could obviously reduceapp:addword:obviously the expression of MMP-2 and MMP-9 in the peri-infarct area compared with vehicle-treated ischemic rats, which gives some evidence that morroniside may protect BBB function after stroke via the suppression of MMPs." (PMID 24979385, 2014). "Although individual MMP expression had been examined at the prolonged time points, such as 24 h, 5, 7, and even 14 days, post stroke, MMP-9, MMP-3, and MMP-2 had not been compared simultaneously and we chose the 24 h time point to detect acute changes." (PMID 39273389, 2024). "In contrast to MMP-9 and MMP-2 expression after r-tPA treatment in ischemic stroke, MMP-3 levels dropped post stroke without r-tPA treatment and further decreased following r-tPA treatment." (PMID 39273389, 2024). "Quantification of the MMP-2 and MMP-9 bands shows increased activity of MMP-9 in stroke patients compared to non-stroke (P < 0.05 in non-stroke vs PI and non-stroke vs R)." (PMID 28290150, 2018). "However, the molecular mechanisms through which MMP-3 inhibition improves stroke outcome independent of downstream MMP-9 and MMP-2 activation remain largely unexplored." (PMID 39000490, 2024).
Stroke (continued). "Overall, our study has highlighted that the thromboinflammatory response post‐stroke is affected by the preceding SARS‐CoV2 infection by enhancing the VWF/ADAMTS13 axis imbalance and does not elevate to the same magnitude the protein levels of MMP‐2, sICAM‐1, and FIX." (PMID 39972966, 2025).
aneurysm (101 papers, 2004 to 2025). Bulging or ballooning in an area of an artery secondary to arterial wall weakening. "Specifically, further studies are needed defining the causal relationship between MMP-2 expression in VSMCs, sex hormones, and aneurysm formation." (PMID 40202792, 2025). "The effect of CAG is, however, more likely caused by decreased MMP-2 activity in the CAG-treated aneurysms produced in vascular smooth muscle cells." (PMID 35203568, 2022). "Several factors related to aneurysm susceptibility (including angiotensin II and nicotine) cause the upregulation of MMP-2 and MMP-9 through aberrantly induced HIF 1-alpha and promote aneurysmal progression." (PMID 31703088, 2019). "As our control group was age-matched with the aneurysm group, the increased active MMP-2 we observed is caused by a genuine increase most likely due to aneurysm formation." (PMID 30794673, 2019). "A significant increase in the MMP-2/tissue inhibitor matrix metalloproteinase (TIMP)-2 ratio has been associated with increased likelihood of BAV aneurysm formation." (PMID 29671812, 2018). "Immunohistochemical localization showed that the particular enzymes associated with aneurysms were plasmin, MMP-2, MMP-9, and MT1-MMP (an activator of MMP2)." (PMID 25922566, 2015). "Later work in rat and mouse models of IA indicated that macrophage infiltration and MMP expression were associated with aneurysm formation, with specific demonstration of MMP-2 and MMP-9 activity." (PMID 25922566, 2015). "It follows that MMP-2 overexpression may be associated with early elastolysis seen in minor aneurysms, and it is observed not only within the aneurysm but in arteries and veins distant from its location." (PMID 35745168, 2022). "The existing studies have shown that MMP2 degrades both elastic and collagen fibers, and the degradation of elastic fibers is associated with aneurysm dilation, while the degradation of collagen fibers is associated with aneurysm rupture." (PMID 35282381, 2022). "MMP-2 has also been associated with the development of aneurysms in the thoracic aorta." (PMID 29483877, 2018). "In addition, S100A12, another DAMP molecule recently recognized as a common ligand of RAGE and TLR4, has been associated with production of IL-6 and MMP-2 and enhancement of aneurysm formation." (PMID 26741694, 2016). "Importantly, MMP-2 or MMP-9-deficient mice fail to develop experimental aneurysms." (PMID 24028184, 2013). "CCR2+ macrophage tissue infiltration was associated with overall aneurysm deterioration, such as severe elastin degradation and increased MMP9 24 and MMP2 25 activity when compared to controls." (PMID 40365294, 2025). "Investigation of aneurysm walls revealed significantly lower macrophage infiltration, and Western blots measured lower MMP-2, MMP-9, and NF-κB in resveratrol-treated groups." (PMID 41155344, 2025). "Specifically, an overexpression of MMP-1, -2, and -9 has been observed in aneurysm walls, with higher levels of MMP-2 and -9 found in ruptured aneurysms." (PMID 39301423, 2024). "The degradation of elastin in aneurysms is primarily mediated by the upregulation of MMPs, particularly MMP-2 and MMP-9, which break down the ECM components, including elastin and collagen." (PMID 39595942, 2024). "Previous work demonstrates that MMP2 plays a central role in the formation and early expansion of AAAs, while MMP9 is more related to late AAA expansion and risk of aneurysm rupture." (PMID 38228786, 2024). "Activation of MMP2 and MMP9 and the arising disruption or loss of ECM significantly affect the integrity of the aortic wall and contribute to aneurysm formation." (PMID 39011492, 2024). "The reduction in aneurysm size correlated with reduced expression of matrix metalloproteinases Mmp2 and Mmp9." (PMID 37686377, 2023). "Regarding this, a positive correlation between TLR4, MMP9, and MMP2 and aneurysm development has been reported." (PMID 37445606, 2023).